BCL2 (BCL2 apoptosis regulator)
Diseases named in the same sentence as BCL2 in open-access papers (continued):
Sharing a sentence is not in itself a finding about the gene and the disease.
B-cell lymphopenia (1 paper, 2018). "B-cell lymphopenia is common among HD patients and is due to an increased apoptosis mediated by a decreased Bcl-2 expression and a resistance to IL-7 and B-cell-activating factor of the TNF family, both necessary for the differentiation and survival of B-cells." (PMID 29963040, 2018).
Barrett’s metaplasia (1 paper, 2021). "Compared with Barrett’s metaplasia (BE) and normal samples, the amount of T lymphocytes with downregulation of BCL-2 was notably increased in EAC." (PMID 34868263, 2021).
benign fibrous histiocytoma (1 paper, 2019). A benign neoplasm composed of fibroblastic spindle cells in a whorled storiform pattern. "Benign fibrous histiocytoma may resemble DFSP, but it is usually negative for CD34 and Bcl-2." (PMID 30703718, 2019).
bile duct cancer (1 paper, 2025). "In vitro experiments showed the ability of CagA-positive Helicobacter species to increase levels of the anti-apoptotic factor Bcl2 and activate NF-kB signaling pathways in co-cultured CCA cells, with the proliferation of bile duct cancer cells." (PMID 40310432, 2025).
BLV infection (1 paper, 2025). "Importantly, this highlights the therapeutic value of targeting NF-κB the BCL-2 axis in HTLV infection, as BCL-2 proteins represent key mediators of resistance to apoptosis." (PMID 41201565, 2025). "Besides the BCL-2 inhibitor, the inhibition of other involved signaling pathways in cell proliferation and apoptosis was also investigated in HTLV infection." (PMID 41201565, 2025). "By directly targeting anti-apoptotic BCL-2 proteins, G3139 could sensitize virus-infected T cells to apoptosis, highlighting the therapeutic importance of modulating BCL-2 in HTLV infection, where survival of transformed T cells underpins disease progression and treatment resistance." (PMID 41201565, 2025). "In PBMCs, reduced BAX expression was observed in HPL animals compared to LPL subjects, suggesting that the increased BCL-2 expression may contribute to negative apoptosis regulation in the mammary gland induced by BLV infection." (PMID 41201565, 2025).
breast disease (1 paper, 2015). "In this study, stable cell lines from pre-malignant MCF10ATG3B mammary epithelial cells, a cell line derived from a human proliferative breast disease model, to express exogenous Bcl-2 was established." (PMID 26091803, 2015).
breast phyllodes tumor (1 paper, 2025). A benign, malignant, or borderline circumscribed biphasic neoplasm that arises from the breast. "Additionally, the immunohistochemical application of CD34, CD117, BCL-2, and Ki67 proves valuable in diagnosing and assessing the prognosis of breast phyllodes tumors." (PMID 40486880, 2025).
bronchogenic carcinoma (1 paper, 2024). A lung carcinoma arising from the bronchial epithelium. "Tipgomut and colleagues also exhibited that melittin inhibited cellular proliferation and apoptosis induction through the Bcl-2 upregulation and MADD downregulation in Chago-K1 human bronchogenic carcinoma cells." (PMID 38445441, 2024).
bronchopulmonary dysplasia (1 paper, 2025). Bronchopulmonary dysplasia is a chronic respiratory disease that results from complications related to lung injury during the treatment of infant acute respiratory distress syndrome in low-birth-weight premature infants or from abnormal lung development in older infants. "Identifying pro-apoptotic proteins that BCL2 counteracts, such as BAX, BAK, and/or BOK, and unraveling their upstream regulators will provide further insights into AMF apoptosis mechanisms, which may be disrupted during impaired alveologenesis in bronchopulmonary dysplasia." (PMID 40492191, 2025).
carcinoma in situ (1 paper, 2004). "This demonstrated that pathological grade and BCL-2 staining were the most powerful independent contributors to any combination, while carcinoma in situ and oestrogen receptor status added least information." (PMID 15138474, 2004). "Only BCL-2 staining and carcinoma in situ seemed promising for patients who had not received adjuvant tamoxifen." (PMID 15138474, 2004). "In that subgroup, the combination of low/negative BCL-2 (<30% cells staining) and absence of carcinoma in situ was seen in 50% of those with poor, but only 12.5% of those with good outcome." (PMID 15138474, 2004).
cataract (1 paper, 2022). Partial or complete opacity of the crystalline lens of one or both eyes that decreases visual acuity and eventually results in blindness. "Further analysis suggested that Bax was down-expressed and Bcl-2 was up-regulated in lens epithelial cells from cataract patients, which were reversed via miR-124-3p inhibitor." (PMID 35170373, 2022).
Cerebellar medulloblastoma (1 paper, 2019). "In desmoplastic cerebellar medulloblastoma Daoy cells, Bcl-2 shows the opposite response to the intrinsic pro-apoptotic protein Bax, which displays increased expression, and decreases over time compared to control cells." (PMID 31319483, 2019).
cerebral artery occlusion (1 paper, 2022). "Furthermore, esculetin exerts anti-apoptosis activity in the mouse model of middle cerebral artery occlusion by up-regulating Bcl-2 expression and down-regulating Bax expression and downstream cleaving caspase-3." (PMID 36547068, 2022).
cerebral malaria (1 paper, 2010). A sequestration of Plasmodium falciparum in the brain, which can cause coma and/or seizures. "For example, treatment with z-VAD, a pan-caspase inhibitor, and overexpression of Bcl-2 in transgenic mice, failed to reduce mortality in experimental cerebral malaria." (PMID 21083888, 2010).
cervical endometriosis (1 paper, 2024).
cheilitis (1 paper, 2016). An inflammatory process affecting the lip. "In our cheilitis AP samples, we observed significant positivity with anti-Bcl-2 (periphery of lymphoid follicles), reflecting an attempt to suppress apoptosis at this site." (PMID 26615506, 2016).
childhood asthma (1 paper, 2013). "We used an informative graph for oxidative stress derived from Gene Ontology and identified several variants in ERBB4, OXR1, and BCL2 with strong evidence for associations with childhood asthma." (PMID 24152222, 2013).
chlamydial infection (1 paper, 2015). "psittaci induce host apoptosis and that chlamydial infection is inhibited by Bcl-2 overexpression." (PMID 26290316, 2015).
cholesteatoma (1 paper, 2012). A pathologic process characterized by the proliferation of keratinizing squamous epithelium resulting in the accumulation of keratin and cells in the middle ear and/or mastoid. "A down-regulation of cIAP1 (BIRC2) was observed, whereas p65 (RELA), cFlip (CFLAR) and Bcl-2 show similar expression levels in cholesteatoma and external auditory skin samples." (PMID 23285167, 2012).
chondroblastoma (1 paper, 2009). A benign, chondroid-producing, well-circumscribed, lytic neoplasm usually arising from the epiphysis of long bones. "Chondroblastomas (5/5) and chondromyxoid fibromas (2/5) were the only tumors with a positive reaction for actin, and all chondroblastomas (n=5) and extraskeletal myxoid chondrosarcomas (n=3) were positive for bcl-2." (PMID 19594492, 2009). "Bcl-2 reactivity was also seen in the chondromyxoid fibromas while the chondroblastomas were negative, indicating different paths of tumorogenesis for these two entities despite their superficial resemblance." (PMID 19594492, 2009).
choroidal neovascularization (1 paper, 2019). An eye disorder described by the growth of new blood vessels that originate from the choroid through a break in the Bruch membrane into the sub–retinal pigment epithelium (sub-RPE) or subretinal space. "We also assessed whether pathologic retinal neovascularization in OIR and laser-induced choroidal neovascularization (CNV) relied on expression of Bcl-2 in pericytes or astrocytes." (PMID 31273232, 2019). "Although pathologic neovascularization in oxygen-induced ischemic retinopathy (OIR) was not affected by lack of expression of Bcl-2 in either pericytes or astrocytes, laser-induced choroidal neovascularization (CNV) was significantly reduced in Bcl-2PC mice compared to littermate controls." (PMID 31273232, 2019).
chronic graft versus host disease (1 paper, 2018). Chronic graft versus host disease (GVHD) is a complication that can occur after a stem cell or bone marrow transplant in which the newly transplanted donor cells attack the transplant recipient's body. "Similarly, in chronic graft-versus-host disease model, PD-1-deficient Tregs showed proapoptotic with a higher Fas and a lower Bcl-2 expression." (PMID 29868037, 2018).
chronic leukemia (1 paper, 2012). A slowly progressing leukemia characterized by a clonal (malignant) proliferation of maturing and mature myeloid cells or mature lymphocytes. "In the present paper, we describe current knowledge on the role of BCL2 apoptosis regulator proteins in acute and chronic leukemias." (PMID 21941553, 2012).
chronic myelomonocytic leukemia (1 paper, 2021). A myelodysplastic/myeloproliferative neoplasm which is characterized by persistent monocytosis, absence of a Philadelphia chromosome and BCR/ABL fusion gene, fewer than 20 percent blasts in the bone marrow and blood, myelodysplasia, and absence of PDGFRA or PDGFRB rearrangement. "We evaluated the expression of BCL2 in bone marrow CD34+ cells from a cohort of MDS and chronic myelomonocytic leukemia patients with and without ASXL1 mutations." (PMID 34548471, 2021).
congenital melanocytic nevus (1 paper, 2025). "BCL2 expression contributes to the prolonged survival of both P16+ senescent and Ki67+ proliferative giant congenital melanocytic nevus (GCMN) cells." (PMID 40374605, 2025).
convulsion (1 paper, 2016). A rapid and repeated body muscle contract that results in an uncontrolled shaking of the body. "In this paper, we utilised a flurothyl-induced recurrent convulsions model, explored whether microRNAs control astrocyte death, and discovered miR-34b-5p connected to astrocyte apoptosis by affecting Bcl-2 mRNA translation." (PMID 27514646, 2016).
cylindroma (1 paper, 2016). "Notably, siRNA knock‐down of MYB in cylindroma cells resulted in down‐regulation of both BCL2 and BIRC3 mRNA levels." (PMID 26969893, 2016).
cystic tumor (1 paper, 2020). "Although the immunohistochemical expression of only two markers is insufficient to prove that OKC is a cystic tumor, our results suggest that SOX2 and BCL-2 are related to the persistent growth potential of OKC, a characteristic compatible with its neoplastic nature." (PMID 31967981, 2020).
demyelinating disease (1 paper, 2023). A broad group of disorders that affect the myelin sheaths that cover the neurons. "Therefore, we used FKBP5-PPAR-γ-Bcl2 as the core and spread outward to search for possible key nodes between CNS demyelinating diseases and mitophagy, and tested the expected accuracy by subsequent experiments." (PMID 37952053, 2023).
Dengue virus infection (1 paper, 2011). "Dengue virus infection leads to CHOP activation but fails to induce any apoptotic markers like suppression of Bcl2 protein levels, activation of caspases or cleavage of poly (ADP-ribose) polymerase." (PMID 21966512, 2011).
dental caries (1 paper, 2024). The decay of a tooth, in which it becomes softened, discolored, and/or porous. "There are seven key proteins involved in the action of curcumin on dental caries: MAPK1, BCL2, KRAS, CXCL8, TGFB1, MMP9, and IL1B, all of which spontaneously bind curcumin." (PMID 38920854, 2024).
dermal neoplasm (1 paper, 2024). "The histopathological examination revealed a rather well-circumscribed dermal neoplasm extending into subcutaneous tissue with high mitotic activity and immunohistochemical positivity for vimentin, CD99, and Bcl-2, but not for markers like CD45, HMB45, and S-100." (PMID 39022482, 2024).
dermatomyositis (1 paper, 2026). Dermatomyositis (DM) is a type of idiopathic inflammatory myopathy characterized by evocative skin lesions and symmetrical proximal muscle weakness. "Network toxicology analysis suggested that BPA may influence the progression of dermatomyositis by regulating key factors such as AKT1, BCL2, MMP9, ESR1, and INS, thereby affecting apoptosis, immune-inflammatory responses, pathways in cancer, and the PI3K-Akt signaling pathway." (PMID 41911226, 2026).
Desminopathy (1 paper, 2016). "So we analyze bax, bcl2,bcl-xl, and HK2 expression and location in the muscle fibersof patients with desminopathy by using immunofluorescences." (PMID 27941998, 2016). "Meanwhile apoptosis related proteins bax and ATF2 were involved in desminopathy patients and desminopathy rat model, but not bcl-2, bcl-xl or HK2.VDAC1 and desmin are closely relevant in the tissue splices of deminopathies patients and rats with desminopathy at protein lever." (PMID 27941998, 2016). "Moreover, apoptotic proteins are also involved in the desminopathies, like bax, ATF2, but not bcl-2, bcl-xl or HK2." (PMID 27941998, 2016).
diabetic foot ulcers (1 paper, 2023). "Specifically, monocytes/macrophages increased expression of several apoptosis genes (including BCL2, FGFR3, FGFR1, CTH, CASP3, IL19, NME5, and S100A8/9) in diabetic foot ulcers compared to monocytes/macrophages in non-diabetic wounds." (PMID 38127424, 2023).
diffuse astrocytoma (1 paper, 2020). A low-grade (WHO grade II) astrocytic neoplasm. "Low WT1 scores in grade II and III diffuse astrocytomas were linked to the high frequency of IDH1 positivity, and were associated with low Bcl2 and Ki67 labelling indices." (PMID 32856872, 2020).
ductal carcinoma in situ (1 paper, 2015). "However, Bcl-2 and Bcl-xL over-expression in combination with oncogene-induced proliferation resulted in lumen filling, a morphological characteristic of ductal carcinoma in situ (DCIS), an early pre-malignant state." (PMID 25784482, 2015).
duodenitis (1 paper, 2023). Acute or chronic inflammation of the duodenum. "In rats with duodenitis, the gene expressions of NF-κB p65 and Bax increased while that of Bcl-2 gene and the Bcl-2/Bax ratio decreased in the duodenal homogenate." (PMID 37255094, 2023).
Dyspareunia (1 paper, 2025). Recurrent or persistent genital pain associated with sexual intercourse. "Epithelial Bcl-2 was positively correlated with the intensity of dyspareunia in the 10 patients with dyspareunia." (PMID 40243611, 2025).
eczema (1 paper, 2019). "Immunohistochemical expression of apoptosis markers (BCL-2 and Survivin) were also investigated in the studied cases compared to normal skin and eczema biopsies." (PMID 31648231, 2019).
Endometrial Intraepithelial Neoplasia (1 paper, 2023). A premalignant neoplastic process that affects the endometrial epithelium and glands. "Another study confirmed this observation in which AM expression increased from benign endometrium to endometrial intraepithelial neoplasia and type-1 adenocarcinoma, but Bcl-2 expression decreased in the transition from endometrial intraepithelial neoplasia to carcinoma." (PMID 36980580, 2023).
endometrial tumors (1 paper, 2018). "However, the results of our study confirmed Bokhman’s scheme, as they showed that DFF40 and BCL2 expression levels were decreased in non-endometrioid and high-grade endometrial tumors compared with grade 1 and 2 ECs." (PMID 29653556, 2018).
epithelial ovarian tumor (1 paper, 2009). "Therefore, we sought to examine Bcl-2 expression in normal, benign, and cancerous ovarian tissues to determine the potential relationship between epithelial and stromal Bcl-2 expression in conjunction with the presence of lymphocytes for epithelial ovarian tumor progression." (PMID 19852858, 2009).
Epstein-Barr virus infection (1 paper, 2017). An infection that is caused by Epstein-Barr virus. "Additionally, the pathway ‘Epstein-Barr virus infection’ was simultaneously enriched, in which several genes including BCL2, CD39, HSP70, HDAC45, IL10, IL10R and vimentin were up-regulated, together with some down-regulated genes such as CD38, NUP214, RBP-Jκ, CycA, TAK1 and TBK1." (PMID 28912500, 2017).
epulis (1 paper, 2021). A non-neoplastic nodular lesion that arises from the gingiva. "The pathogenesis of fibrous epulis is still quite unclear, and apoptosis inhibition through the overexpression of Bcl‐2 may play an important role in the process of epulis." (PMID 33934404, 2021). "In another study, we identified the expression of 84 apoptotic genes in epulis using a Qiagen RT2 Profiler PCR Array, and the results indicated that the overexpression of antiapoptotic genes in the Bcl‐2 and IAP families inhibits apoptosis in gingival tissues, which eventually causes epulis." (PMID 33934404, 2021).
erythroblastic leukemia (1 paper, 2017). "The potential oncogenic nature of Fli-1 was previously demonstrated in erythroblastic leukemia, wherein Fli-1 was shown to induce the proliferation of differentiation-arrested erythroblasts with longer survival of Fli-1 expressing with BCL2 expression." (PMID 28418872, 2017).
fibromyalgia (1 paper, 2021). A chronic disorder of unknown etiology characterized by pain, stiffness, and tenderness in the muscles of neck, shoulders, back, hips, arms, and legs. "Reserpine-induced fibromyalgia was associated with stimulated apoptosis, as shown by the significant increase in caspase-3 expression and decreased Bcl-2 mRNA gene expression in the carotid artery and in the cerebral cortex." (PMID 35011610, 2021).
Fibrous Meningioma (1 paper, 2020). A WHO grade I meningioma characterized by the presence of spindle cells that form bundles in a collagen matrix. "Besides, compared with SFT, a fibrous meningioma is usually better stained by an EMA antibody, but only mildly or focally positive on CD34 and Bcl-2 staining." (PMID 33327290, 2020).
Flavivirus Infections (1 paper, 2019). Infections with viruses of the genus FLAVIVIRUS, family FLAVIVIRIDAE. "Anti-apoptotic protein Bcl-2 has been shown to play a role in the protection from apoptosis during flavivirus infection." (PMID 31658698, 2019).
frontotemporal dementia (1 paper, 2021). Frontotemporal dementia (FTD) comprises a group of neurodegenerative disorders, characterized by progressive changes in behavior, executive dysfunction and language impairment, as a result of degeneration of the medial prefrontal and frontoinsular cortices. "The BCL2 protein, involved in the mitochondrial outer membrane permeabilization, is overexpressed in CNS disorders, such as AD, PD, and frontotemporal dementia (FTD), whereas it undergoes downregulation in tumors." (PMID 34073579, 2021).
Fulminant hepatic failure (1 paper, 2013). Hepatic failure refers to the inability of the liver to perform its normal synthetic and metabolic functions, which can result in coagulopathy and alteration in the mental status of a previously healthy individual. "The pim-3 gene also protected rats from fulminant hepatic failure by inhibiting liver apoptosis and improving the inflammatory response of liver tissues, which was associated with inhibiting the expression of inflammatory mediators and promoting the production of the anti-apoptosis protein Bcl-2." (PMID 23825534, 2013).